ENSG00000255872 (novel transcript)
Gene: Protein-coding gene on chromosome 9 (37,588,413 to 38,068,687, reverse strand). Ensembl gene ENSG00000255872.
Genetic constraint (gnomAD): Missense variants: 552 observed, 301.16 expected, observed/expected ratio (o/e) 1.83, 90% interval 1.71 to 1.95. Synonymous variants: 277 observed, 143.43 expected, observed/expected ratio (o/e) 1.93, 90% interval 1.73 to 1.99.